PRCP (prolylcarboxypeptidase)
Diseases named in the same sentence as PRCP in open-access papers (continued):
Sharing a sentence is not in itself a finding about the gene and the disease.
cancer (4 papers, 2018 to 2025). A tumor composed of atypical neoplastic, often pleomorphic cells that invade other tissues. "It will be important in the future to explore PRCP expression in other cancer types and to identify PRCPi drug combinations that can most effectively inhibit tumor growth." (PMID 35159006, 2022). "They found that this treatment significantly promoted PrCP of different types of viable human cancer cells by both human and mouse macrophages." (PMID 30405101, 2018). "Findings in the current study that high tumor expression of PRCP correlates with worse outcomes in TNBC patients suggest its ability to promote RTK signaling may lead to more aggressive tumors, as well as further indicate the prognostic potential of PRCP is not limited to ER+ cancers." (PMID 35159006, 2022). "Most of these proteins are recognized as potential prognostic biomarkers in liver (TFRC and GPLD1), renal (IGHG1, PRCP, SAA1/2, and IL1RAP) and digestive (PRSS3) cancers in the Human Protein Atlas database." (PMID 41155404, 2025). "A role for PRCP in TNBC or other cancers, and its potential as a therapy target has not yet been tested." (PMID 35159006, 2022). "Inhibition of PRCP with a small molecule inhibitor blocked TNBC cell and tumor growth and inhibited the activity of several receptor tyrosine kinases (RTKs), proteins that are located on the surface of cells and that are important for cancer development and progression." (PMID 35159006, 2022). "A role for PRCP in TNBC or other cancers has, to date, not been widely appreciated." (PMID 35159006, 2022). "A potential role for PRCP in cancer has to date not been widely appreciated." (PMID 36332175, 2022).
cardiovascular disease (3 papers, 2016 to 2024). "Association of cardiovascular disease outcomes with SNPs in the PRCP and KLKB1 genes controlling for age, weight, and gender." (PMID 27200353, 2016). "In the present investigation, we asked if polymorphisms of PRCP and PK are associated with cardiovascular disease (CVD)." (PMID 27200353, 2016). "A cross-sectional investigation determined if there is an association of PRCP and KLKB1 polymorphisms with cardiovascular disease (CVD)." (PMID 27200353, 2016).
tumor (3 papers, 2009 to 2025). "In the current study we found high tumor expression of PRCP is associated with worse outcome and earlier recurrence in TNBC patients." (PMID 35159006, 2022). "High tumor expression of PRCP associates with worse outcome and earlier recurrence in TNBC patients." (PMID 35159006, 2022). "In the current study, we found high tumor expression of PRCP associates with worse outcome and earlier recurrence in TNBC patients." (PMID 35159006, 2022). "The findings support the idea that PRCP contributes to tumor growth and demonstrate that PRCPi has anti-tumor activity in vivo." (PMID 35159006, 2022). "shRNA-mediated knockdown of PRCP or treatment with a small-molecule inhibitor of PRCP reduced TNBC cell survival and proliferation and blocked TNBC tumor growth in mice." (PMID 35159006, 2022).
infection (2 papers, 2009 to 2021). The state of being infected such as from the introduction of a foreign agent such as serum, vaccine, antigenic substance or organism. "It was also proved that nbe-miR167b-3p responded to the infection of TbCSV by regulating the expression of its target gene PRCP." (PMID 34975814, 2021). "It will be of interest to determine if PRCP plays a pathophysiological role in modulating des-Arg9-bradykinin in infection and in other clinically relevant disease situations." (PMID 19171072, 2009). "In this study, it was disclosed that the infection of TbCSV could be enhanced by suppressed nbe-miR167b-3p expression and nbe-miR167b-3p responded to the infection of TbCSV by regulating the expression of its target gene PRCP." (PMID 34975814, 2021).
PRCP also shares sentences with these, for which no sentence is quoted: diabetes (3 papers); Breast Tumor (2); Nephropathy (2); acute coronary syndrome (1); angina (1); cataract (1); cystic fibrosis (1); essential hypertension (1); Hyperglycemia (1); ischemic stroke (1); rheumatoid arthritis (1); Shock (1); Stroke (1).